KXD1 (KxDL motif containing 1)
Description:
As part of the BORC complex may play a role in lysosomes movement and localization at the cell periphery. Associated with the cytosolic face of lysosomes, the BORC complex may recruit ARL8B and couple lysosomes to microtubule plus-end-directed kinesin motor. May be involved in the biogenesis of lysosome-related organelles such as melanosomes (By similarity).
Synonyms: C19orf50; FLJ25480; MGC2749; KXDL; BORCS4; C10orf50; MST096; MSTP096
Tractability: PROTAC: ubiquitination databases record sites on it; its protein half-life has been measured.
Gene: Protein-coding gene on chromosome 19 (18,557,683 to 18,569,387, forward strand). Ensembl gene ENSG00000105700.
Subcellular location: Lysosome membrane
Subcellular location (Human Protein Atlas): Centrosome; Cytosol; Nucleoli fibrillar center
Gene Ontology:
Molecular function: protein binding
Biological process: lysosome localization; organelle transport along microtubule; regulation of endosome size; regulation of lysosome size; vesicle-mediated transport
Cellular component: BORC complex; BLOC-1 complex; cytoplasmic side of lysosomal membrane; lysosomal membrane
Genetic constraint (gnomAD): Loss-of-function variants: 7 observed, 13.94 expected, observed/expected ratio (o/e) 0.5, 90% interval 0.28 to 0.94. The upper end of that interval is the gene's LOEUF score, 0.94, which puts it in group 4 of 6, group 1 being the genes least tolerant of losing a copy. Missense variants: 192 observed, 247.37 expected, observed/expected ratio (o/e) 0.78, 90% interval 0.69 to 0.88. Synonymous variants: 97 observed, 102.74 expected, observed/expected ratio (o/e) 0.94, 90% interval 0.8 to 1.12.
Homologues: Orthologues: macaque KXD1 (99% identical), dog KXD1 (94% identical), pig KXD1 (94% identical), mouse Kxd1 (93% identical), rat Kxd1 (90% identical), tropical clawed frog kxd1 (64% identical), zebrafish kxd1 (61% identical), Drosophila melanogaster CG10681 (38% identical), Caenorhabditis elegans kxd-1 (20% identical).
Diseases named in the same sentence as KXD1 in open-access papers:
KXD1 is named in the same sentence as 3 diseases in open-access papers, as found by Europe PMC text mining. Sharing a sentence is not in itself a finding about the gene and the disease. The quoted sentences say what the papers report.
depression (1 paper, 2024). "In depression, changes in the expression of genes related to a better response to antidepressants (MMO28 and KXD1 genes) have been identified." (PMID 39595828, 2024).
cancer (1 paper, 2021). A tumor composed of atypical neoplastic, often pleomorphic cells that invade other tissues. "In NSCLC, KXD1 overexpression was positively correlated with cancer invasion and metastasis and negatively correlated with non-surgical anti-cancer treatment resistance." (PMID 35096017, 2021).
KXD1 also shares sentences with these, for which no sentence is quoted: Meckel syndrome (1 paper).